RSPO2 (R-spondin 2)
Diseases named in the same sentence as RSPO2 in open-access papers (continued):
Sharing a sentence is not in itself a finding about the gene and the disease.
infection (4 papers, 2016 to 2022). The state of being infected such as from the introduction of a foreign agent such as serum, vaccine, antigenic substance or organism. "We previously reported that Rspo2 is a major genetic determinant of the outcome of C. rodentium infection; Rspo2 induction during infection of susceptible mice leads to loss of intestinal function and mortality." (PMID 29339782, 2018). "Rspo2 is robustly induced during infection in susceptible mouse strains, leading to pathological activation of Wnt signaling, generation of a poorly differentiated colonic epithelium, and animal death." (PMID 29339782, 2018). "Susceptible mice (e.g. C3H/HeOuJ) share a unique genetic haplotype immediately upstream of Rspo2, driving high levels of Rspo2 in susceptible mouse strains during infection and leading to pathological activation of Wnt signaling, loss of intestinal differentiation, and animal death." (PMID 27046199, 2016). "To extend our data to the in vivo situation, we first generated an adeno-associated virus (AAV) system to express RSPO2 under the chicken β-actin promoter (CAG), while pAAV–CAG–GFP was used as infection control." (PMID 35027768, 2022). "We previously identified the Rspo2 gene to control the outcome to C. rodentium infection in mice; it localizes to the minimal genetic region governing infection outcome and is induced to high levels specifically in susceptible mice." (PMID 29339782, 2018). "To determine if the downregulation of Rspo1 and Rspo3 was potentially a compensatory response to the increase in Rspo2 during infection, we assessed R-spondin levels in resistant C3Ou.B6-Cri1 congenic mice at days 3, 6, and 9 post-infection." (PMID 27046199, 2016). "Consistent with our previous data, we found the Rspo2 gene to be strongly and continuously induced during infection." (PMID 27046199, 2016). "While our data supports the hypothesis that Rspo2 induction in inflamed or infected tissue could augment CRC disease, it is difficult to address considering infection-susceptible mice display high mortality following C. rodentium infection." (PMID 29339782, 2018). "Our unique parental and congenic strains, differing only in their expression of Rspo2 during infection, therefore provide a more accurate experimental model system to study the biological effects of Rspo2 on disease tolerance as compared to those based on genetically divergent inbred mouse strains." (PMID 29339782, 2018). "Our analysis highlighted changes in host metabolism and tissue remodeling as common responses to infection while providing evidence for a role of antigen processing and presentation of MHC II molecules in disease tolerance as a direct or indirect consequence of Rspo2 induction in susceptible mice." (PMID 29339782, 2018). "In contrast, resistant mice that do not express Rspo2 following infection still develop colonic epithelial hyperplasia at the peak of infection but suffer milder, self-limiting disease without experiencing a loss of intestinal function." (PMID 29339782, 2018). "In contrast, C3H/HeOuJ mice carrying a congenic segment encompassing Rspo2 and its regulatory region from resistant mice (C3Ou.B6-Cri1) do not upregulate Rspo2 during infection, and instead suffer from self-limiting disease with no mortality." (PMID 27046199, 2016). "When pAAV–CAG–Rspo2 was injected into one depot of ingWAT in mice, while the other depot received pAAV–CAG–GFP as a control, RSPO2 protein levels were twofold higher, whereas mRNA levels were around 100-fold higher than pAAV–CAG–GFP-injected depots 6 weeks after infection." (PMID 35027768, 2022).
digestive system cancer (1 paper, 2018). A primary or metastatic malignant neoplasm involving any part of the digestive system. "The RSPO2 fusion will serve as a good biomarker for screening patients to support clinical treatment of digestive system cancers using Wnt pathway inhibitors." (PMID 30250044, 2018).
metabolic disease (1 paper, 2022). A congenital disorder (due to inherited enzyme abnormality) or acquired (due to failure of a metabolically important organ) disorder resulting from an abnormal metabolic process. "Also in human studies, RSPO2 expression within adipose tissue and its relation to metabolic diseases will require a fractionation of adipose tissue in larger patient cohorts." (PMID 35027768, 2022).
RSPO2 also shares sentences with these, for which no sentence is quoted: acute lymphocytic leukemia (2 papers); cholangiocarcinoma (2); glioblastoma (2); liver cancer (2); bone metastasis (1); colorectal adenoma (1); congenital myasthenic syndrome (1); Crohn disease (1); diabetic kidney disease (1); endometrial cancer (1); Familial adenomatous polyposis (1); glaucoma (1); hepatocellular adenoma (1); Hydroureter (1); infectious colitis (1); inflammatory bowel disease (1); invasive breast carcinoma (1); kidney (1); Kidney Cyst (1); liver fibrosis (1); mastitis (1); metastasis (1); metastatic prostate carcinoma (1); nasopharyngeal carcinoma (1); optic atrophy (1); Osteopenia (1); osteopetrosis (1); Peyronie disease (1); polycystic kidney (1); Premature ovarian insufficiency (1).
A further 2 diseases each share a sentence with RSPO2 in 1 paper.